CLEC4A (C-type lectin domain family 4 member A)
Diseases named in the same sentence as CLEC4A in open-access papers:
CLEC4A is named in the same sentence as 60 diseases in open-access papers, as found by Europe PMC text mining. Sharing a sentence is not in itself a finding about the gene and the disease. The quoted sentences say what the papers report.
autoimmune disease (10 papers, 2009 to 2026). A disorder resulting from loss of function or tissue destruction of an organ or multiple organs, arising from humoral or cellular immune responses of the individual to their own tissue constituents. "Since Clec4a is a negative immune regulator of DCs, mice deficient in Clec4a develop autoimmune diseases due to excess expansion of activated DCs and CD4+ T cells." (PMID 37892972, 2023).
colitis (7 papers, 2014 to 2024). Inflammation of the colon. "CLEC4A has been demonstrated to have an impact on colon inflammation and the onset of colitis in particular." (PMID 38037545, 2023).
rheumatoid arthritis (7 papers, 2010 to 2025). A chronic, systemic autoimmune disorder characterized by inflammation in the synovial membranes and articular surfaces. "CLEC4A was implicated in Tuberculosis, Hematopoietic Cell Lineage, Cell Adhesion Molecules, Th1 and Th2 Cell Differentiation, Rheumatoid Arthritis, Central Carbon Metabolism in Cancer, AMPK Signaling Pathway, Biosynthesis of Amino Acids, Cysteine and Methionine Metabolism, and Tyrosine Metabolism." (PMID 40607411, 2025).
Arthritis (5 papers, 2009 to 2025). Inflammation of a joint. "Previously, we investigated whether natural polymorphisms in rat Clec4a isoforms regulate PIA, but it turned out that Clec4a-containing congenic fragments failed to influence arthritis." (PMID 35052516, 2021).
colorectal cancer (3 papers, 2024). A primary or metastatic malignant neoplasm that affects the colon or rectum. "By analyzing publicly available cancer transcriptomic data, we found a positive association between high CLEC4A expression and prolonged survival in patients with colorectal cancer (CRC)." (PMID 38532110, 2024).
melanoma (3 papers, 2022 to 2025). A malignant, usually aggressive tumor composed of atypical, neoplastic melanocytes. "While this mutation is a strong driver of melanoma proliferation, our findings demonstrate that modulating CLEC4A expression still significantly impacted proliferation, migration, and invasion in this BRAF-mutant context." (PMID 40607411, 2025). "Together, these results suggest that CLEC4A plays a critical role in regulating melanoma cell motility and invasiveness, functioning as a potential molecular brake in melanoma progression." (PMID 40607411, 2025). "Immunohistochemical analysis of melanoma and benign nevi further corroborated these findings, showing a marked decrease in CLEC4A protein levels in malignant melanoma tissues." (PMID 40607411, 2025). "The expression and clinical significance of CLEC4A in melanoma were comprehensively evaluated by comparing data from TCGA-SKCM and GTEX-Skin datasets." (PMID 40607411, 2025). "A preliminary expression profiling across various melanoma cell lines revealed differential CLEC4A expression patterns, with the A375 cell line exhibiting relatively lower CLEC4A levels when compared to SK-MEL-2 and MV3, yet higher levels compared to A2058." (PMID 40607411, 2025). "Analysis revealed that CLEC4A expression is significantly lower in melanoma tissues compared to normal skin." (PMID 40607411, 2025). "Regarding CLEC4A specifically, its reduced expression in melanoma tissues compared to benign nevi, a trend initially suggested by our analysis of transcriptomic databases and confirmed by immunohistochemical staining of tissue sections." (PMID 40607411, 2025). "Functional assays demonstrated that downregulation of CLEC4A significantly promoted melanoma cell proliferation, migration, and invasion." (PMID 40607411, 2025). "The three-gene KRAS-Macrophage Prognostic Associated Gene (KMPAG) signature, encompassing CLEC4A, CXCL10, and LAT2, emerges as a robust prognostic tool that correlates with distinct clinical and immunological phenotypes in melanoma cohorts." (PMID 40607411, 2025). "Consistent with the mRNA levels and IHC staining, Western blot analysis also revealed a notable reduction in CLEC4A protein expression in melanoma tissues compared to benign nevi, with this pattern being reproducible across replicates." (PMID 40607411, 2025). "This concordance across multiple independent detection methodologies significantly strengthens the reliability of CLEC4A’s diminished expression as a consistent molecular feature in melanoma, reinforcing its potential role and prognostic significance." (PMID 40607411, 2025). "RT-qPCR results demonstrated that CLEC4A mRNA expression was significantly lower in melanoma tissues (n=12) compared to benign nevi (n=8) (P < 0.001)." (PMID 40607411, 2025). "Our experimental validation focused on the functional role of CLEC4A through knockdown and overexpression in the A375 melanoma cell line." (PMID 40607411, 2025). "Functional Role of CLEC4A: Downregulation of CLEC4A significantly enhanced melanoma cell proliferation, migration, and invasion, suggesting its potential as a therapeutic target." (PMID 40607411, 2025). "Of note, correlations between CLEC4A expression and tumor-infiltration of several innate and adaptive immune cells were also reported in (cutaneous) melanoma and hepatocarcinoma, suggesting that DCIR regulates the immune response in multiple types of cancer." (PMID 38532110, 2024). "This suggests that reduced CLEC4A expression may serve as an indicator of disease progression in melanoma." (PMID 40607411, 2025). "Further exploration of CLEC4A’s role in melanoma progression may provide new therapeutic avenues for targeted intervention." (PMID 40607411, 2025). "For CLEC4A, five miRNAs (hsa-miR-1206, hsa-miR-1266-3p, hsa-miR-488-5p, hsa-miR-5589-3p, and hsa-miR-6873-3p) were consistently predicted across all four databases, suggesting a robust regulatory role in modulating CLEC4A expression in melanoma." (PMID 40607411, 2025).
melanoma (continued). "Future experiments using macrophage cell lines (THP-1 differentiated macrophages) or primary human macrophages with CLEC4A modulation are crucial to understand its role in macrophage polarization, phagocytosis, or antigen presentation in the context of melanoma." (PMID 40607411, 2025). "The macrophage-centric gene signature described in this study, comprising CLEC4A, CXCL10, and LAT2, furnishes robust evidence that macrophages can vary widely in their functional states within melanoma lesions." (PMID 40607411, 2025). "Moreover, CLEC4A expression exhibited significant correlations with CXCL10 (r = 0.706) and LAT2 (r = 0.851), suggesting potential cooperative roles of these genes in melanoma." (PMID 40607411, 2025).
systemic lupus erythematosus (3 papers, 2023 to 2025). An autoimmune multi-organ disease typically associated with vasculopathy and autoantibody production. "Furthermore, pathway interaction analyses revealed that CLEC4A was significantly associated with Allograft Rejection, Butanoate Metabolism, Graft-versus-host Disease, Histidine Metabolism, Systemic Lupus Erythematosus, and Valine, Leucine, and Isoleucine Degradation pathways." (PMID 40607411, 2025).
colon cancer (2 papers, 2024). "Further analysis of TCGA data reveals a significant decrease in CLEC4A expression from stage I to stage IV of colon cancer." (PMID 38532110, 2024). "Moreover, CLEC4A expression is associated with longer overall survival of patients with stage I, III, and IV colon cancer (HR < 1), although it is only significant in stage III." (PMID 38532110, 2024).
COVID-19 (2 papers, 2021 to 2023). A disease caused by infection with severe acute respiratory syndrome coronavirus 2. "Among these, four (CLEC4A, DSG4, FAM3B, and RARRES1) displayed significantly lower levels in both moderate and severe COVID-19, as compared to the healthy controls and the sepsis cohorts." (PMID 36829233, 2023).
fungal infection (2 papers, 2022 to 2025). "In fungal infections, CLEC4A recognizes Pneumocystis spp; however, its effector function remains unclear." (PMID 40831560, 2025).
hepatocellular carcinoma (2 papers, 2021 to 2023). A malignant tumor that arises from hepatocytes. "We found significantly higher mRNA levels of CLEC4A and CLEC4L in HCC tissues compared to normal liver tissues, whereas the expression of CLEC4G/H1/H2/M was significantly lower in liver carcinoma." (PMID 34409028, 2021).
joint ankylosis (2 papers, 2016 to 2023). "Of the 7,408 genes tested,CLEC4A (C-type lectin domain family 4, member A) demonstrated the strongest association with joint effusion grades in the knee (effect size=0.407 (SE=0.120); p-value =9.57E-04)." (PMID 27134727, 2016).
liver cancer (1 paper, 2021). An epithelial or non-epithelial malignant neoplasm that arises from the liver. "The IHC analysis revealed the following: Absence of CLEC4A/J/K/M in normal and liver cancer tissues; high CLEC4C expression in HCC tissues; low expression and zero detection of CLEC4D/E/H1/H2/L in HCC tissues and normal tissues, respectively." (PMID 34409028, 2021). "The IHC results revealed no CLEC4A/G/J/K/M in normal and liver cancer tissues, whereas CLEC4C was highly expressed in HCC tissues, and CLEC4H1/H2 was lower expressed in HCC tissues compared to normal tissues." (PMID 34409028, 2021).
psoriasis (1 paper, 2023). An autoimmune condition characterized by red, well-delineated plaques with silvery scales that are usually on the extensor surfaces and scalp. "For the regulatory DC transcriptome, the proportion of regulatory semimature DCs expressing regulatory DC markers of BDCA-3 (THBD) and DCIR (CLEC4A) was increased in posttreatment psoriasis lesional skin compared to pretreatment psoriasis lesional skin." (PMID 37781383, 2023).
pulmonary disease (1 paper, 2022). "The NLRP3 MFI on CD3 positive of early-stage NSCLC patients showed higher expression than non-malignant pulmonary disease whereas C5AR1 and CLEC4A expression levels were not different." (PMID 36323738, 2022). "The median ratios of C5AR1, CLEC4A and NLRP3 expression in CD3+ of non-malignant pulmonary diseases were 0.01 [range 0–0.02, p = 0.12], 0.02 [range 0.01–0.08, p = 0.42] and 0.13 [range 0.07–0.22, p = 0.14], respectively." (PMID 36323738, 2022).
renal carcinoma (1 paper, 2024). A carcinoma arising from the epithelium of the renal parenchyma or the renal pelvis. "Among the most significant results, high CLEC4A expression was associated with poor prognostic in testis and renal cancer." (PMID 38532110, 2024).
infection (15 papers, 2010 to 2024). The state of being infected such as from the introduction of a foreign agent such as serum, vaccine, antigenic substance or organism. "We found that Mincle/Clec4a and Clec5a transcription was significantly abrogated upon Syk inhibition at 6 h of infection." (PMID 36678402, 2022). "DCs expressing Clec4a inhibit inflammatory responses and T cell immunity during infections." (PMID 37892972, 2023).
tumor (12 papers, 2010 to 2025). "We next analyzed the association of CLEC4A expression with multiple tumor parameters including high microsatellite instability (MSI-H) tumors and consensus molecular subtypes (CMS)." (PMID 38532110, 2024). "Further exploration of the relationship between CLEC4s and tumor grade revealed that a significant association of the expression of CLEC4A/F/G/H1/H2/M with tumor grade." (PMID 34409028, 2021). "Interestingly, expression levels of MHC I (HLA-A) and costimulatory receptors such as CD86, ICOSLG, and CLEC4A were high in tumor-associated CD206+ Macro_C1QC even compared with tumor-associated cDC1_CLEC9A." (PMID 35503656, 2022). "Moreover, mechanistic evidence indicating a tumor-suppressive role for CLEC4A suggests that fine-tuning key macrophage-associated genes may complement existing immunotherapies." (PMID 40607411, 2025). "The immune landscape within the tumor microenvironment was assessed, revealing a strong positive correlation (r = 0.726) between CLEC4A expression and macrophage infiltration." (PMID 40607411, 2025). "Altogether, these data indicate that CLEC4A is expressed both at the mRNA and protein levels in human CRC tumors and suggest that DCIR regulates the anti-tumor immune response in CRC." (PMID 38532110, 2024). "CLEC4A expression is also associated with immune cell infiltration and high immunologic constant of tumor rejection, suggesting a protective role for DCIR during CRC development." (PMID 38532110, 2024). "We have previously shown that downregulation of DCIR expression in DCs via gene gun-mediated delivery of Clec4a shRNA inhibits tumor growth and enhances CD8+ T cell immunity in the murine MBT-2 tumor model." (PMID 37892972, 2023). "One study described the role of CLEC4A down-regulation via small hairpin RNA inhibiting tumor progression in animal models." (PMID 36323738, 2022). "Further analysis of the expression level of CLEC4s between unpaired tumor samples and normal controls revealed significantly low CLEC4A/D/E/G/H1/J/M levels expressed in HCC samples." (PMID 34409028, 2021). "The proposed KMPAG signature underscores the importance of three genes—CLEC4A, CXCL10, and LAT2—in modulating tumor–immune crosstalk and predicting patient outcomes." (PMID 40607411, 2025). "Second, we found positive correlations between CLEC4A expression and the presence of different innate immune cell subtypes in the CRC tumor, which is not surprising at first glance considering that DCIR is mainly expressed by myeloid cells." (PMID 38532110, 2024). "In the current study, we employed strategies of tumor-selective virotherapy and silencing of the negative immune regulator Clec4a to generate Ad.shDCIR." (PMID 37892972, 2023). "However, the expression of CLEC4A, CLEC4D, CLEC4E, CLEC4J (FCER2), CLEC4K (CD207), CLEC4G, CLEC4H1, CLEC4M, and CLEC4H2 decreased with tumor progression." (PMID 34409028, 2021). "Three significant up-regulated genes which had the presence of antibody-specific, immunohistochemistry-based protein expression on tumor-infiltrating lymphocytes (TILs) in tumor specimen, but not in normal lymphoid tissue, were selected including CLEC4A, C5AR1, NLRP3." (PMID 36323738, 2022). "We selected C5AR1, CLEC4A and NLRP3 based on their significant protein expression in tumor-infiltrating lymphocytes, but not in normal lymphoid tissue." (PMID 36323738, 2022).
cancer (9 papers, 2021 to 2026). A tumor composed of atypical neoplastic, often pleomorphic cells that invade other tissues. "Several proteins positively associated with MVPA are inversely associated with disease risk (e.g., integrins, CLEC4A for cancer; LPL, LEP for T2D), while proteins negatively associated with MVPA are positively associated with disease risk (e.g., CD38, TGFA for CVD)." (PMID 41826625, 2026). "In contrast, up-regulation of other members from this superfamily such as CLEC18B, CLEC5A, CLEC4A, and CLEC4L were reported to be associated with development, proliferation, migration, and invasion in cancer cells." (PMID 38167030, 2024). "CLEC4A is expressed in all major human cancer types, although its expression varies from one type of cancer to another." (PMID 38532110, 2024). "Moreover, depending on the cancer type, CLEC4A appears to be either an unfavorable or a favorable prognostic gene, meaning that a higher CLEC4A expression correlated with a shorter or longer patients’ life expectancy, respectively." (PMID 38532110, 2024). "Second, the results of this study could not serve the explanation of pathophysiological relevance of diverse expression of C5AR1, CLEC4A and NLRP3 in CD3+ T-lymphocyte amount cancer patient and healthy individuals." (PMID 36323738, 2022).
cardiovascular diseases (1 paper, 2022). "Fostering the homeostatic functions of macrophages through the CLEC4A pathway might represent a transformative therapeutic strategy for inflammatory and cardiovascular diseases." (PMID 35017526, 2022).
CLEC4A also shares sentences with these, for which no sentence is quoted: Autoimmunity (5 papers); HIV-1 infection (4); tuberculosis (4); AIDS (3); airway hyperresponsiveness (2); allergic disease (2); atopic dermatitis (2); viral infections (2); Allergy (1); anaphylaxis (1); asthma (1); autoimmune encephalitis (1); bacterial infections (1); bladder tumors (1); chronic obstructive pulmonary disease (1); co-infections (1); Crohn disease (1); depression (1); dysplasia (1); encephalomyelitis (1); enthesitis (1); experimental autoimmune encephalomyelitis (1); glioblastoma (1); gouty arthritis (1); hidradenitis suppurativa (1); inflammatory bowel disease (1); influenza (1); joint effusion (1); non-small cell lung carcinoma (1); osteoporosis (1).
A further 10 diseases each share a sentence with CLEC4A in 1 paper.